COMT (catechol-O-methyltransferase)
Diseases named in the same sentence as COMT in open-access papers (continued):
Sharing a sentence is not in itself a finding about the gene and the disease.
osteoarthritis (4 papers, 2019 to 2025). A noninflammatory degenerative joint disease occurring chiefly in older persons, characterized by degeneration of the articular cartilage, hypertrophy of bone at the margins and changes in the synovial membrane. "Recently, evidence has emerged that the analgesic effects of TENS for knee pain associated with osteoarthritis is influenced by genetic variation within the catechol-O-methyltransferase (COMT) and endothelin receptor type A (EDNRA) genes." (PMID 33919821, 2021). "In osteoarthritis, the low-activity allele of COMT [158Met or A] was associated with increased hip pain in patients with damaged hip." (PMID 30704436, 2019). "Building on this knowledge, the present study investigates how polymorphisms in the OPRM1 and COMT genes are associated with analgesic requirements in diabetic and non-diabetic patients with osteoarthritis (OA) following total hip or knee arthroplasty." (PMID 40649008, 2025).
behavioral addictions (3 papers, 2020 to 2025). "Several studies have explored the association between COMT rs4680 and impulsivity across different populations, including healthy individuals, psychiatric patients, and those with substance use or behavioral addictions." (PMID 41465775, 2025). "The aim of the study was to investigate the association of the COMT gene polymorphism with behavioral addiction." (PMID 38540358, 2024). "Results add to previous work on COMT inhibitors in behavioral addictions and to mounting evidence for the applicability of diffusion models in value-based decision-making." (PMID 32341121, 2020). "A significant interaction effect was observed between the COMT rs4680 genotype and group status (behavioral addiction vs. control) on the BIS Non-Planning Impulsivity (NI) scores (F2,303 = 4.40, p = 0.0131, η2 = 0.028)." (PMID 41465775, 2025).
bladder cancer (3 papers, 2018 to 2023). "However, some studies stated otherwise, where low enzyme activity of the COMT gene decreases the risk of bladder cancer among men." (PMID 34209963, 2021). "Data about the relationship between COMT polymorphism and bladder cancer risk are limited." (PMID 30042310, 2018). "However, Wolpert showed an association between the low- or intermediate activity COMT genotypes (MetMet or ValMet) and decreased susceptibility to bladder cancer among Egyptian men and premenopausal women." (PMID 30042310, 2018). "The four-locus models (APE1, RAD52, COMT, and MTHFR) for bladder cancer provided a prediction error of 0.78 and a CVC of 6.60 and 0.78 with a CVC of 7.40." (PMID 38137497, 2023).
diabetic kidney disease (3 papers, 2008 to 2021). Progressive kidney disorder caused by vascular damage to the glomerular capillaries, in patients with diabetes mellitus. "Among them, CAT and OGG1 are downregulated, and CASP3, COMT, CYP1B1, DPYD, NQO1, and PTGS1 are upregulated in diabetic kidney disease (DKD) tubuli." (PMID 34367469, 2021).
Dystonia (3 papers, 2014 to 2022). An abnormally increased muscular tone that causes fixed abnormal postures. "Given the patient’s genetic condition, we hypothesized that the dopaminergic dysfunction had been aggravated by COMT involvement, thus causing dystonia." (PMID 34679357, 2021). "Authors hypothesized that an imbalance between dopaminergic and muscarinic receptors activity in the nigrostriatal pathway could support the role of COMT in the onset of dystonia in the patient treated." (PMID 34679357, 2021).
endothelial dysfunction (3 papers, 2017 to 2018). In vascular diseases, endothelial dysfunction is a systemic pathological state of the endothelium (the inner lining of blood vessels) and can be broadly defined as an imbalance between vasodilating and vasoconstricting substances produced by (or acting on) the endothelium. "Schizophrenic individuals carrying at least one MTHFR T and/or COMT Val risk allele have a lower RH-PAT index, reflective of greater endothelial dysfunction and lower frontal executive functions, compared with MTHFR CC and COMT Met/Met genotypes." (PMID 28588507, 2017).
epilepsy (3 papers, 2006 to 2026). A brain disorder characterized by episodes of abnormally increased neuronal discharge resulting in transient episodes of sensory or motor neurological dysfunction, or psychic dysfunction. "Epilepsy-related proteins, including upregulation of GRM1 and COMT and downregulation of PDGFRB and OTX2, were noted." (PMID 41597222, 2026).
Glucose intolerance (3 papers, 2017 to 2024). Glucose intolerance (GI) can be defined as dysglycemia that comprises both prediabetes and diabetes. "Here, we report that COMT deficiency leads to glucose intolerance and 2-ME rescues COMT-deficient-associated metabolic defects." (PMID 28801594, 2017). "In high-fat diet mouse models, using COMT inhibitors exacerbated glucose intolerance, led to increased lipid deposition in the liver, and enhanced macrophage accumulation." (PMID 39280009, 2024). "IPGTT analysis exhibited a remarkable exacerbation in the glucose intolerance in the COMT siRNA-treated HFD-fed mice compared with scramble siRNA-treated HFD-fed mice." (PMID 28801594, 2017). "Treatment with the COMT inhibitor for the last 1 week exacerbated glucose intolerance in HFD mice." (PMID 28801594, 2017). "COMT suppression, by Ro41-0960 or siRNA, in HFD fed mice or in pregnant mice exacerbated glucose intolerance; 2-ME intervention ameliorated these defects." (PMID 28801594, 2017).
gout (3 papers, 2015 to 2025). A condition characterized by painful swelling of the joints, which is caused by deposition of urate crystals. "In this study, we, for the first time, demonstrate that a common missense variant of COMT, rs4680, plays a protective role in the pathogenesis of gout." (PMID 26147675, 2015). "In the present study, we aimed to test variants in the LRP2 and COMT genes, both of which are abundantly expressed in the kidney, for associations with uric acid and gout in a Chinese population." (PMID 26147675, 2015). "Our study aims to test variants in two genes abundantly expressed in the kidney, LRP2 and COMT, for their association with uric acid and gout." (PMID 26147675, 2015). "Research indicates that the COMT rs4680 (Val158Met) variant may prevent gout and potentially influence gout through regulation of dopamine levels." (PMID 41311848, 2025). "There is a significant association between COMT hypomethylation and the risk of gout in men, and COMT hypomethylation may serve as a potential diagnostic biomarker for gout in the future." (PMID 41311848, 2025). "Therefore, it is necessary to identify novel candidate loci, such as COMT, for associations with uric acid and gout." (PMID 26147675, 2015). "The present study provides the first evidence for an association between COMT and gout." (PMID 26147675, 2015). "A Chinese study showed that rs4680 (V158M) of COMT gene was associated with gout, but the association was negative in a Taiwanese aborigines population." (PMID 30123371, 2018). "In this study, we revealed that rs4680G>A plays a protective role in the development of gout, suggesting that rs4680 in COMT might influence the development of gout by regulating dopamine levels." (PMID 26147675, 2015). "Therefore, further studies of LRP2 and COMT genes in larger samples will be performed to confirm the relationship between these loci and gout together with gene-environment interactions." (PMID 26147675, 2015). "Thus, COMT may be a candidate gene in the pathogenesis of gout." (PMID 26147675, 2015).
ischemic heart disease (3 papers, 2008 to 2018). "Results indicated that COMT rs4680 G > A polymorphism is associated with susceptibility to coronary artery disease, providing novel insights into the genetic etiology and underlying biology of this disease." (PMID 30011860, 2018). "Our findings indicated that common COMT polymorphism is associated with an increased risk of coronary artery disease events." (PMID 30011860, 2018). "Our findings showed that COMT rs4680 G > A polymorphism is associated with an increased risk of coronary artery disease for COMT-GA vs. GG genotype (OR = 3.5, 95% CI 1.58–7.74; RR 1.62, 95% CI 1.25–2.10; p = 0.0002) in the codominant inheritance model." (PMID 30011860, 2018). "Many recent epidemiologic studies have investigated the association between the COMT Val158Met polymorphism and coronary artery diseases risk, but the results are inconclusive." (PMID 30011860, 2018). "An increased risk of coronary artery disease was observed in the codominant inheritance model for COMT-GA vs. GG genotype with an OR of 3.5, 95% CI (1.58–7.74) p = 0.002) and COMT-AA vs. GG genotype with an OR of 6.0 95% CI (2.11–17.3) p = 0.003)." (PMID 30011860, 2018). "In addition, our population-based case control study has reported that this genetic variation in COMT is associated with increased risk of coronary heart disease." (PMID 30011860, 2018). "Therefore, we determined that COMT rs4680 G > A polymorphism leads to a 6.0-, 3.5-, and 1.8-fold increase in the risk of developing coronary artery disease in Indian populations." (PMID 30011860, 2018). "Furthermore, links between COMT genotypes and the increased risk of coronary events or the outcome of patients with ischemic heart disease were revealed." (PMID 30011860, 2018). "COMT Val158Met polymorphism leads to a 6.0, 3.5 and 1.8-fold increased risk of developing coronary artery disease in the Indian population and providing novel insights into the genetic etiology and underlying biology of coronary artery disease." (PMID 30011860, 2018). "Furthermore, links between COMT genotypes and the increased risk of coronary events or the outcome of patients with ischemic heart disease have been revealed." (PMID 30011860, 2018). "Also the results indicated that the COMT-AA genotype and A allele are significantly associated with an increased susceptibility to coronary artery disease." (PMID 30011860, 2018). "Therefore our study was aimed to explore the association between COMT Val158Met polymorphism and the risk of coronary artery disease in India." (PMID 30011860, 2018). "The higher risk of coronary artery disease was observed in the dominant inheritance model for COMT (GA + AA) vs. GG genotype (OR 3.85, 95% CI 1.76–8.4, p < 0.007), whereas a non-significant association was found in recessive model for COMT (GG + GA vs. AA) (OR = 2.01, 95% CI (0.86–4.7) p = 0.72)." (PMID 30011860, 2018). "The individuals with known genotype were significantly older and had, consequently, higher blood pressure and cholesterol level, higher prevalence of ischemic heart disease and chronic musculoskeletal pain, and had lower physical activity level than those with unknown COMT genotype." (PMID 18578865, 2008).
pancreatic cancer (3 papers, 2017 to 2021). "Also, lower COMT expression led to reduced survival time and overall survival for patients with pancreatic cancer." (PMID 34587154, 2021). "In addition, overexpression of COMT has been found in pancreatic cancer tissue." (PMID 34209963, 2021).
psoriasis (3 papers, 2009 to 2024). An autoimmune condition characterized by red, well-delineated plaques with silvery scales that are usually on the extensor surfaces and scalp. "Moreover, aggregation of upregulating COMT-mediated catecholamines can cause a long-lasting inflammatory skin disease called psoriasis, which produces red/brown-colored apoptotic cells." (PMID 38956500, 2024). "Catechol-O-methyltransferase (COMT) 158 polymorphism can reduce the activity of the COMT enzyme that may trigger defective differentiation of keratinocytes in psoriasis." (PMID 21637643, 2009).
rest tremor (3 papers, 2012 to 2021). "The results indicate that PD patients carrying COMT rs4680(A) have a higher chance of having more severe bradykinesia in the upper extremity and rest tremor than PD patients with the rs4680(GG) genotype." (PMID 33808974, 2021).
trauma (3 papers, 2016 to 2025). "In contact sports, the COMT rs4680 polymorphism has been correlated with susceptibility to head trauma and elite athlete status, while CD36 rs1761667 has been associated with the risk of non-contact injuries." (PMID 41010024, 2025). "COMT and DRD2 are involved in dopaminergic transmission, which is altered after head trauma and contributes to changes in cognition and behavior." (PMID 41301762, 2025).
Uterine leiomyoma (3 papers, 2009 to 2023). The presence of a leiomyoma of the uterus. "COMT over expression or treatment with 2ME stabilize microtubules, ameliorates E2-induced proliferation, inhibits ERα and PR signaling, and reduces HIF-1 α and CYP19 expression in human uterine leiomyoma cells." (PMID 19809499, 2009).
Visual hallucination (3 papers, 2019 to 2022). Visual perception in the absence of a visual stimulus. "In addition, COMT haplotypes have been associated with the development of visual hallucinations in PD patients in this study." (PMID 35741861, 2022). "Interestingly, COMT-DDC gene–gene interaction has been shown to affect the risk of levodopa-induced visual hallucinations in PD patients." (PMID 35741861, 2022). "Additionally, haplotypes of COMT and SLC6A3 were associated with the occurrence of visual hallucinations (AT vs. GC: OR = 0.34; 95% CI = 0.16–0.72; p = 0.005) and orthostatic hypotension (ATG vs. ACG: OR = 2.48; 95% CI: 1.01–6.07; p = 0.047), respectively." (PMID 30745869, 2019).
amyloid (2 papers, 2018 to 2020). "For example, the genetic expression of COMT and the effect of the dopamine system can be influenced by aging, amyloid load, and disease severity." (PMID 28707072, 2018).
Arrhythmia (2 papers, 2007 to 2025). Any cardiac rhythm other than the normal sinus rhythm. "Val/Val genotype is associated with high COMT enzyme activity, and speculatively, rapid metabolism of circulating catecholamines may be protective for some type of heart diseases e.g. the arrhythmias." (PMID 17577421, 2007). "Levodopa is commonly taken with aromatic L-amino acid decarboxylase (AADC) inhibitors like carbidopa or benserazide and catechol-O-methyltransferase (COMT) inhibitors to improve bioavailability and reduce peripheral side effects like cardiac arrhythmias, hypotension, nausea, and vomiting." (PMID 40791686, 2025).
binge eating disorder (2 papers, 2023 to 2024). Recurrent episodes of over-eating. "For instance, an investigation into the influence of the COMT polymorphism on behavioral impulsivity in the binge eating disorder found that patients within the BED group that were homozygous for the risk allele showed stronger deficits in inhibitory control." (PMID 37511777, 2023).
cervical cancer (2 papers, 2016 to 2017). A primary or metastatic malignant neoplasm involving the cervix. "We observed that the genotypes for CYP1A1 and COMT for intermediate activity represented the highest risk for developing cervical cancer of that observed individually for COMT genotype that was protector." (PMID 26798414, 2016). "This is the first study in Portugal that exposes the interaction of CYP1A1 and COMT polymorphisms in cervical cancer." (PMID 26798414, 2016). "The lower activity of COMT represents a higher risk for cervical cancer and so does the highest activity of CYP1A1." (PMID 26798414, 2016). "We studied the association of CYP1A1 M1 (rs4646903) and COMT (rs4680) polymorphisms in 130 cervical cancer cases (c-cancer) and 179 controls." (PMID 26798414, 2016). "We performed the determination of CYP1A1 (rs4646903) and COMT (rs4680) polymorphisms in 130 women with cervical cancer and 180 healthy women." (PMID 26798414, 2016). "The COMT polymorphism possibly represents a more important role for protection than that of risk for cervical cancer." (PMID 26798414, 2016). "We also observed that the CYP1A1&COMT TC&HH might increase the risk for cervical cancer, though with a wide confidence interval (OR = 13.67, 95% CI = 1.72–109.39, p = 0.014) (data not shown)." (PMID 26798414, 2016). "To investigate whether profiles of CYP1A1 and COMT genotypes might be associated with the risk of cervical cancer, we examined the effect combinations of genotypes." (PMID 26798414, 2016). "When evaluating the risk for cervical cancer associated with the COMT genotypes, we observed that the best model was the COMT LL genotype, which could represent up to 5 times more risk (OR = 4.83, 95% CI = 2.08–11.20, p < 0.001)." (PMID 26798414, 2016). "Recently, the relationships between some other polymorphisms and cervical cancer development were investigated, such as CYP1A1 MspI (rs4646903), COMT (rs4680), and CYP2E1 (rs3813867) polymorphisms." (PMID 29326607, 2017). "The highest risk for cervical cancer was for the association of CYP1A1&COMT TC&HL (OR = 6.07, 95% CI = 1.67–22.09, p = 0.006), without adjusting for age." (PMID 26798414, 2016). "So, an association study of functional polymorphisms involved in synthesis of 2-methoxy-estradiol, namely, CYP1A1 (rs4646903) and COMT (rs4680), could contribute to understanding the role of estrogen in cervical cancer." (PMID 26798414, 2016). "Because the enzymes COMT and CYP1A1 are closely related and work in metabolic sequence in the metabolism of estrogens, it is important to examine if the functional polymorphisms of these enzymes in association change the risk to develop cervical cancer in the carriers." (PMID 26798414, 2016). "Although not statistically significant, we observed that cervical cancer patients had higher values of estradiol in COMT LL genotype (data not shown)." (PMID 26798414, 2016).
cognition (2 papers, 2015 to 2016). Intellectual or mental process whereby an organism becomes aware of or obtains knowledge. "As previous associations link cognition deficits to treatment with SGAs and COMT variant alleles in the BD population, we hypothesize this COMT variant would result in decreased cognitive scores in BD patients who are treated with SGAs." (PMID 27039372, 2016). "Although it is not possible in the present paradigm to draw conclusions about the consequences of resting-state EEG power on the behavioral, emotional and cognitive changes reported in the COMT genotypes, some interesting correlations may be considered and deserve further investigation." (PMID 25883560, 2015).
colon carcinoma (2 papers, 2012 to 2021). "Studies on miRNA regulation of COMT is highly limited in cancer and in the only known report, a polymorphism in the 3’UTR region of COMT could significantly reduce the binding of miR-22 in colon cancer cells." (PMID 34587154, 2021).
drug dependence (2 papers, 2021 to 2022). "We evidenced, for the first time, that, in individuals with SUD, s-COMT activity was correlated with the severity of drug dependence (EuropASI) (p = 0.009), and with BIS-11 factors self-control (p < 0.0001) and non-planning (p = 0.002)." (PMID 35729517, 2022).
Impaired glucose tolerance (2 papers, 2009 to 2025). An abnormal resistance to glucose, i.e., a reduction in the ability to maintain glucose levels in the blood stream within normal limits following oral or intravenous administration of glucose. "Notably, its metabolic significance has been highlighted in studies on HFD-fed and pregnant mice, wherein reduced COMT activity was associated with impaired glucose tolerance." (PMID 40868264, 2025).
influenza (2 papers, 2022 to 2024). An acute viral infection of the respiratory tract, occurring in isolated cases, in epidemics, or in pandemics; it is caused by serologically different strains of viruses (influenzaviruses) designated A, B, and C, has a 3-day incubation period, and usually lasts for 3 to 10 days. "However, we could not determine this in detail across the four conditions because the COMT genotypes in the Pro and Y-Elite dancers were unbalanced in this study, as some of the dancers were absent due to influenza on the measurement day." (PMID 39590895, 2024).